TLR7 (toll like receptor 7)
Diseases named in the same sentence as TLR7 in open-access papers (continued):
Sharing a sentence is not in itself a finding about the gene and the disease.
tumor (continued). "Therefore, R848 induced activation of pDCs through TLR7/8 in turn activates immature tumor-infiltration cDCs to become able to induce antitumor immunity." (PMID 30619338, 2018). "Interestingly, a TLR7 agonist was shown to be effective at reversing the pro-tumor phenotype of murine TAMs in vitro, but only in combination with TGF-β blockade." (PMID 29123526, 2017). "Here we have demonstrated that for obinutuzumab, when given in combination with a systemic TLR7 agonist, long-term tumor-free survival appears to be dependent on NK cells and CD4+ T cells with macrophages and monocytes only able to mediate short-term increases in survival." (PMID 27890931, 2017). "TLR7 agonist is known to impart tumor killing activity to plasmacytoid dendritic cells (pDCs)." (PMID 28036266, 2017). "Another adjuvant, co-administration of the TLR7 agonist imiquimod led to improved antitumor effect of cancer vaccine augmenting tumor specific immune response based on the decline of tumor infiltrating MDSCs and on the activation of antitumor NK 1.1+ and F4/80+ macrophages." (PMID 27886105, 2016). "In addition, imiquimod is a potent inducer of apoptosis in human tumour cell lines via TLR7 independent mechanisms." (PMID 27936237, 2016). "Interestingly, in both human cancers TLR7 and -8 expression was related rather to cancer cells and rarely detected in tumor-infiltrating immune cells." (PMID 27941651, 2016). "Comparison of the cellular co-localization of TLR7 or TLR8 with CD34 analyzed by immunofluorescence double staining revealed increased coexpression of TLR7 or TLR8 with CD34 in tumor cells, indicating that those cells were indeed cancer cells expressing the angiogenic surface molecule." (PMID 26134824, 2015). "The rationale of the therapeutic combination was that radiotherapy would provide tumor antigens, while the TLR7/8 agonist would stimulate antigen-presenting cells to process and present these antigens in order to induce and augment an immune response to the tumor." (PMID 25609199, 2015). "In addition to the eradication of large primary tumours, the combined application targeting TLR7, 8 and 9 also established long-term antitumour immunity." (PMID 25887995, 2015). "More importantly, TLR7/TLR8 expression increased tumor growth in vivo." (PMID 26134824, 2015). "Interestingly, the anti-tumor effects of the combination of TLR7/8 agonist and radiation appeared to be entirely mediated by CD8 T cells." (PMID 25609199, 2015). "In addition, some research results suggest that enforcement of innate immunity by targeted TLR activation has beneficial effects to combat tumor growth, like TLR7 agonist imiquimod, licensed for therapy of basal cell carcinoma." (PMID 26134824, 2015). "Topical treatment of melanoma, with IMQ, a TLR-7 agonist, has been shown to facilitate 1) tumor infiltration with immune effector cells such as activated, cytotoxic plasmacytoid DCs, 2) a type I IFN response, 3) anti-angiogenic defenses, and in some cases result in complete tumor regression." (PMID 29546098, 2015). "In addition, our novel concept was supported by studies from other groups showing anti-tumor activity mediated by TLR7 and TLR8 ligands." (PMID 25231413, 2014). "However, evidence of TLR3 and TLR7 tumor-promotion has been reported for other cancers such as in lung, pancreas, and liver." (PMID 25411122, 2014). "However, TLR7 surrogate ligand induced downregulation of MHC class 1 molecule on tumor cells resulting in a reduced affinity for inhibitory receptor NKG2A on γδ T cells." (PMID 25132835, 2014). "Remarkably, a recent study by He and colleagues showed that tumor-secreted microvesicles contain an elevated expression of microRNA-21 (miR-21) and induce myoblast apoptosis in cancer cachexia via a Toll-like receptor 7-c-Jun N-terminal kinase-dependent pathway." (PMID 25238546, 2014).
tumor (continued). "Taken together, these findings suggest that enhancing the TLR7 expression in immune cells may potentiate the anti-tumor effect of combination chemotherapy in advanced stage NSCLC patients." (PMID 23451142, 2013). "Indeed, the anti-tumor activities of Imiquimod, a ligand for TLR7, and CpG DNA, a ligand for TLR9, have been demonstrated in several clinical trials." (PMID 24098333, 2013). "By another group, exosomal miR-21 and miR-29a was shown to activate Toll-like receptor 7 and 8 in immune cells, triggering a prometastatic inflammatory response that may lead to tumor growth and metastasis." (PMID 23519132, 2013). "In addition, the TLR7/8 vaccine preparation evoked an arrest of tumor volume growth in rats carrying large tumors that were treated before with the antigen only vaccine preparation." (PMID 24955288, 2012). "R-848 has been found to be a TLR7/8 agonist with demonstrated antiviral and anti-tumor activity." (PMID 22243920, 2012). "In the current study, we explored the combination of the DNA vaccine encoding calreticulin (CRT) linked to human papillomavirus type 16 (HPV-16) E7 antigen (CRT/E7) with the TLR7 agonist imiquimod for their ability to generate E7-specific immune responses and antitumor effects in tumor-bearing mice." (PMID 20426849, 2010). "Their more recent studies showed that tumor antigen plus agonistic anti-CD40 antibody combined with a TLR7 agonist reduced B16F10 lung metastases in mice, though the treatment began only four days after the intravenous injection of tumor cells, rather than being tested on established tumors." (PMID 19812695, 2009). "However, some studies have indicated that agonists targeting TLR7 may activate innate immune pathways and boost anti-tumor responses, providing a potential avenue for therapeutic intervention." (PMID 41157253, 2025). "Despite these limitations, the data presented here provide important insights into the immune responses induced by TLR7a, TLR9a, and TLR7/8a encapsulated in VLPs, and suggests that TLR7/8a VLPs may be most efficacious in vivo at inducing an anti-tumor immune response." (PMID 41249948, 2025). "Studies have shown that mannosylated nanoparticles delivering the TLR7/8 agonist R848 (Man-pD-PLGA-NP@R848) target tumor-associated macrophages (TAMs) through mannose receptor-mediated endocytosis, inducing their transition from the M2 (pro-tumor) to the M1 (anti-tumor) phenotype." (PMID 41488647, 2025). "However, approximately 15–25% of X-chromosomal genes escape XCI (termed “escape genes”), many of which exhibit higher expression levels in females than males, particularly those involved in immunity and tumor suppression, such as Toll-like receptor 7 (TLR7) and KDM6A." (PMID 41019050, 2025). "Furthermore, TLR7/8 activation promotes tumor cell apoptosis and strengthens antitumor immunity." (PMID 41228373, 2025). "Therefore, TLR7/8a VLPs may potentially induce a robust anti-tumor immune response and warrant further investigation for cancer therapy." (PMID 41249948, 2025). "Consequently, the ability of TLR7 agonists to effectively activate cells within the myeloid system, thus exerting anti-tumor activity in the tumor microenvironment, may be compromised." (PMID 39346737, 2024). "Thus, we sought to investigate whether the combination of DSP-0509, an AXL inhibitor, and TLR7 agonist induces robust activation of myeloid cells, resulting in a potent anti-tumor response within the tumor microenvironment." (PMID 39346737, 2024). "Moreover, the outcomes of the mentioned study suggested that TLR7 could promote an immune suppressive microenvironment that facilitates the promotion of the immune evasion capacity of the tumor cells." (PMID 37822929, 2023). "However, tumor infiltration by pDCs has been correlated with a poor prognosis for patients with various cancers, supposedly due to their impaired response to TLR7/9 activation and decreased IFN-α release, thereby contributing to the production of IL-10, TGF-β, and Treg cells." (PMID 36768258, 2023).
tumor (continued). "TLR7 may have opposing functions in tumor versus stroma cells." (PMID 36602302, 2023). "However, high TLR7 expression in the tumor correlated with statistically significantly reduced overall survival with all long‐time survivors (>36 months after diagnosis) showing weak to moderate TLR7 expression." (PMID 36602302, 2023). "Regardless, early systemic chemokine induction following TransCon TLR7/8 Agonist treatment correlated with an increase in peripheral NK and myeloid cells, suggesting mobilization of cells that may participate in tumor killing and tumor antigen presentation, respectively." (PMID 36123697, 2022). "However, we already demonstrated the immunogenicity of the non-glycosylated MUC1 peptide in previous work, and the combination of the naked MUC1 sequence and the TLR7 agonist (T7 + MUC1) could be an effective tumor vaccine." (PMID 36499455, 2022). "Additionally, TLR7 and TLR8 are the only two members that exhibit a significant positive link with the level of immune and interstitial cell infiltration in all 33 cancer types, implying that TLR7 and TLR8 are associated with low tumour purity." (PMID 35801728, 2022). "TDEs also engage with other TLRs such as TLR4 and TLR7 on other phagocytes including monocytes and neutrophils in which miRNA, noncoding RNA, and high-mobility group box 1 (HMGB1) transferred by TDEs are implicated in driving the pro-tumor phenotype of these myeloid cells." (PMID 36031601, 2022). "A meta-analysis of the prognostic role of TLRs in cancer showed that higher expression levels of TLR7 in tumor tissues could predict poorer survival, suggesting the expression level of TLR7 in cancerous tissue may have a prognostic value in patients with various cancers." (PMID 36476317, 2022). "In parallel, to evaluate whether TLR7 silencing could affect the tumorigenic potential of A549 cells, we xenografted shCTR (a mass population) and shTLR7 (two clones) A549 cells (5 × 106 cells) in athymic mice and monitored tumor growth rate." (PMID 33578955, 2021). "Since a previous study revealed that enhanced production of CCL2 from tumor tissue may be involved in TLR7/8-induced antitumor effects, we also evaluated Ccl2 expression in MC38 cells in the presence of IMQ and found that IMQ significantly upregulated the expression of Ccl2 in MC38 cells." (PMID 34439104, 2021). "In addition to the anti-angiogenesis induced by chelation of Cu2+, these smart nanoparticles caused further anti-tumor effects via tumor vessel obstruction (e.g., aggregation of nanochelators) and TLR-mediated immune cells stimulation (with TLR7 and TLR8 agonist), respectively." (PMID 32328480, 2020). "Our work indicates that disruption of the vicious circle involving STAT3 signaling in the tumor microenvironment, along with the stimulation of TLR7/8 signaling, could induce effective antitumor immune responses without toxicity and chemotherapy-associated side effects." (PMID 33679700, 2020). "Significant tumour growth inhibition was achieved when combining intratumoural telratolimod with systemic agonistic anti-OX40 compared to either agent given alone, which may be due to observed increases in OX40 receptor expression in treated tumours as a result of TLR7/8 agonism." (PMID 33352882, 2020). "In addition to the delivery of IDO inhibitors and TLR7/8 agonists, nanoparticles could also be used to deliver tumor antigens." (PMID 32328428, 2020). "Thus, TLR7 agonists may synergize with MEK1/2 inhibitor to augment the anti-tumor treatment efficacy." (PMID 31507609, 2019). "Furthermore, it was hypothesized that retention of the TLR7/8 agonist in the tumor may be important for efficacy." (PMID 31511088, 2019). "In addition to DNA and protein content, it is possible that chemotherapy may also trigger the release of RNA from dying tumor cells, which can in turn serve as a ligand for TLR7 or TLR8." (PMID 31619293, 2019).
tumor (continued). "Interestingly, when SCC samples were treated with a TLR-7 agonist, imiquimod, tumor vessels up-regulated E-selectin expression causing an increase in CLA+ CD8+ T cell influx into the tumor, a decrease in Treg frequency and tumor regression." (PMID 31231358, 2019). "Finally, the presence of a solid and bulky tumor, as seen in our experiment, may hamper both optimal TLR-7 activation as well as an efficient cellular response resulting in antitumor efficacy." (PMID 29767328, 2018). "Interestingly, the moderate potency TLR-7/8a led to T cell responses that were balanced between effectors and memory cells, which may be optimal for tumor vaccines." (PMID 30400835, 2018). "Instead, many studies have indicated that TLR agonists alone may have detrimental clinical effects by creating an inflammatory environment favourable for tumour growth, although whether the effects promote or inhibit tumour growth appears to depend on the specific TLR7." (PMID 29415982, 2018). "Furthermore, tumor‐released miRNA binds murine TLR7 and human TLR8 in immune cells, leading to TLR‐induced prometastatic inflammatory response that may ultimately lead to tumor metastasis." (PMID 28665028, 2017). "In addition to targeting additional co-inhibitory and co-stimulatory pathways, combination with standards of care or targeted therapies that lead to tumor cell stress and/or death may improve the immunogenicity of TLR7 therapy." (PMID 26959743, 2016). "However, for many other cancer types, systemic or intra-tumoral delivery of TLR7 agonists may be required to elicit anti-tumor immune responses." (PMID 26959743, 2016). "For the treatment of noncutaneous tumors, systemic administration of a TLR7 agonist may be required to stimulate an immune response with the capacity to modify the tumor-associated milieu and/or facilitate T-cell priming through activation of APCs." (PMID 24390981, 2014). "Thus, TLR7 or TLR9 agonists may promote anti-tumor activity directly or via other immune mechanisms." (PMID 18652679, 2008). "We evaluated the therapeutic synergism between intratumoral injection of oxaliplatin (OxPt) and the imidazoquinoline TLR7/8 agonist 1-(4-(aminomethyl)benzyl)-2-butyl-1H-imidazo[4,5-c]quinolin-4-amine (IMDQ) in a syngeneic CT26 mouse tumor model." (PMID 40230629, 2025). "In lung cancer cells, TLR7 and TLR8 expressions enhance tumor cell survival and resistance to chemoresistance." (PMID 40495154, 2025). "In human cancers, such as basal cell carcinoma, it has been demonstrated that pDCs stimulated via TLR7 (e.g., with imiquimod, CpG—cytosine-phosphate-guanine, IFN-α) acquired the ability to induce tumor cell apoptosis in a TRAIL-dependent manner." (PMID 40725022, 2025). "In contrast, other loci, including RNGTT, the TLR7 and TLR8 loci, and CDH4, are constitutively or inducibly expressed also in healthy tissue and their expression in tumours is downregulated by the independent transcriptional activation of nearby RTEs." (PMID 40336011, 2025). "TLR7 and TLR8, as conserved innate immune molecules, play a significant role in the tumor microenvironment." (PMID 40469310, 2025). "CFRI-mediated PTT and TLR7 agonist release promoted DC maturation, enhancing CD8+ and CD4+ T cell activity, key for tumor elimination and preventing metastasis." (PMID 40040955, 2025). "TLR7 can activate Th1 cells in DC cells by mediating the IFN–STAT1 signaling pathway, mediating the immune response against AML and preventing tumor cells from escaping immune surveillance." (PMID 40727252, 2025). "A self-assembly nanovaccine, containing the TLR7/8 agonist and STAT3 inhibitor, enhances tumor immunotherapy by augmenting the tumor-specific immune response." (PMID 40573919, 2025). "Toll-like receptors (TLRs), including TLR2, TLR4, TLR7, TLR8, and TLR9, are critical pattern recognition receptors on TAMs, with diverse ligands such as tumor proteins, acute-phase proteins, drugs, and bacterial metabolites." (PMID 40948759, 2025).
tumor (continued). "TLR7 agonists stimulate immune cells to secrete various cytokines, such as IFN-α and TNF-α, thereby enhancing the body’s anti-tumor capacity." (PMID 41488647, 2025). "As discussed in Section 2 and Section 3, receptors such as TLR2, TLR4, TLR7, TLR9 and NLRP3 generally promote tumor progression and immune suppression." (PMID 41157253, 2025). "For instance, the lipophilic TLR7/8 agonist MEDI9197 demonstrated improved retention at the injection site, underscoring the challenges of systemic transport and tumor localization." (PMID 41228373, 2025). "Using bioinformatics and prognostic models, combined with tumor-node-metastasis (TNM) staging of the tumors, the link between TLR7 expression and prognostic factors in LUAD was further elucidated." (PMID 39857735, 2025). "The tumor histology of tumor-infiltrating immune cell subsets (CD4+, CD8+, CD11c+) reveals significant increases in CD11c+ populations, consistent with TLR7/8 agonism." (PMID 40573201, 2025). "A pro-tumour effect of tumour cell-intrinsic TLR7 and TLR8 expression would predict that their downregulation by HERVH Xp22.2-AS transcriptional activation has an anti-tumour effect." (PMID 40336011, 2025). "Combined with a self-assembling nanoparticle vaccine and TLR7 agonist, this method elicits robust CD8+ T cell responses and synergizes with immune checkpoint inhibitors, demonstrating strong tumor suppression and extended survival in preclinical models." (PMID 40083927, 2025). "Various tumor-driven mechanisms can impair CD8+ T cells’ activation and function, limiting the effectiveness of TLR7/8 agonists." (PMID 41228373, 2025). "In preclinical tumor models, intratumoral injection of a TLR2 agonist or targeted delivery of nanoparticles loaded with a TLR7/8 agonist have also been demonstrated to induce repolarization of TAMs towards an anti-tumor phenotype." (PMID 39596395, 2024). "Tumor-derived PGE2 and TGF-β were shown to act in synergy to inhibit the production of IFN-α and TNF-α induced in TLR7- and TLR9-triggered pDCs, by decreasing TLR membrane expression or by blocking TLR downstream signaling." (PMID 38504978, 2024). "For example, the activation of TLR7 and TLR9 in stromal cells or transformed epithelial cells can promote tumor progression." (PMID 38390872, 2024). "miR-21 also stimulates Toll-like receptors TLR7 and TLR8 in immune cells to promote tumor growth and metastasis." (PMID 39409003, 2024). "NEs loaded with toll-like receptor 7/8 (TLR7/8) agonists and tumor antigens activated DCs and T cells while modulating the immunosuppressive tumor microenvironment." (PMID 38543304, 2024). "TLR7 was then activated, which set off a type I IFN response and selective immunomodulation of the tumor microenvironment (TME), which was marked by the activation of T cells and myeloid cell proliferation." (PMID 39456611, 2024). "Agonists for TLRs (TLR3, TLR4, TLR7/8, and TLR9) have been investigated in clinical trials as agents for tumor therapy." (PMID 39516356, 2024). "The reduced expression of TLR7 and TLR9 induced by the immunosuppressive tumor microenvironment in pDCs was also demonstrated in ovarian and breast cancers." (PMID 38504978, 2024). "We have synthesized DSP-0509, a systemic injectable TLR7 agonist, and in this investigation, we examined the effects of DSP-0509 on tumor-infiltrating lymphocytes (TILs) utilizing single-cell RNA sequencing (scRNA-seq) in a mouse model bearing tumors." (PMID 39346737, 2024). "The activation of TLR-2 and TLR-9 by PCa cells appears to promote tumour growth; conversely, the activation of TLR-3, TLR-5, and TLR-7 has been suggested as a potential way to prevent PCa." (PMID 39201739, 2024). "Subsequently, we attempted to perform immunohistochemistry (IHC) staining for NRGs (CYBB, ITGB2, ITGAM, LILRB2, TLR2, and TLR7) in kidney sections from ANCA-GN patients and age- and sex-matched ccRCC patients with adjacent non-tumor tissues." (PMID 37465687, 2023).